DHRS7 (dehydrogenase/reductase 7)
Description:
NADPH-dependent oxidoreductase which catalyzes the reduction of a variety of compounds bearing carbonyl groups including steroids, retinoids and xenobiotics. Catalyzes the reduction/inactivation of 5alpha-dihydrotestosterone to 3alpha-androstanediol, with a possible role in the modulation of androgen receptor function. Involved in the reduction of all-trans-retinal to all-trans-retinol. Converts cortisone to 20beta-dihydrocortisone in vitro, although the physiological relevance of this activity is questionable. Reduces exogenous compounds such as quinones (1,2-naphtoquinone, 9,10-phenantrenequinone and benzoquinone) and other xenobiotics (alpha-diketones) in vitro, suggesting a role in the biotransformation of xenobiotics with carbonyl group. A dehydrogenase activity has not been detected so far. May play a role as tumor suppressor.
Synonyms: retSDR4; SDR34C1; CGI-86; retDSR4
Tractability: Antibody: UniProt predicts a signal peptide or a membrane-spanning region. PROTAC: ubiquitination databases record sites on it; its protein half-life has been measured.
Gene: Protein-coding gene on chromosome 14 (60,144,119 to 60,169,856, reverse strand). Ensembl gene ENSG00000100612.
Subcellular location: Endoplasmic reticulum membrane
Subcellular location (Human Protein Atlas): Mitochondria; Nucleoplasm
Gene Ontology:
Molecular function: all-trans-retinol dehydrogenase (NADP+) activity; carbonyl reductase (NADPH) activity; oxidoreductase activity, acting on the CH-OH group of donors, NAD or NADP as acceptor; protein binding; 3-alpha-hydroxysteroid 3-dehydrogenase [NAD(P)+] activity
Biological process: retinol metabolic process
Cellular component: endoplasmic reticulum membrane; membrane
Genetic constraint (gnomAD): Loss-of-function variants: 33 observed, 34.14 expected, observed/expected ratio (o/e) 0.97, 90% interval 0.73 to 1.29. The upper end of that interval is the gene's LOEUF score, 1.29, which puts it in group 5 of 6, group 1 being the genes least tolerant of losing a copy. Missense variants: 407 observed, 390.91 expected, observed/expected ratio (o/e) 1.04, 90% interval 0.96 to 1.13. Synonymous variants: 149 observed, 143.37 expected, observed/expected ratio (o/e) 1.04, 90% interval 0.91 to 1.19.
Homologues: Orthologues: chimpanzee DHRS7 (99% identical), macaque DHRS7 (96% identical), rabbit DHRS7 (84% identical), pig DHRS7 (83% identical), dog DHRS7 (82% identical), mouse Dhrs7 (79% identical), rat Dhrs7 (77% identical), mouse Dhrs7l (63% identical), rat LOC120093108 (60% identical), rat Dhrs7l1 (60% identical), tropical clawed frog dhrs7 (49% identical), zebrafish dhrs7 (45% identical), and 8 more. Paralogues in human: DHRS7B (25% identical), DHRS7C (22% identical), HSD11B1 (22% identical), RDH8 (20% identical), HSD11B1L (19% identical), DHRS11 (18% identical), DHRS4 (18% identical), DHRS2 (18% identical), HSDL2 (16% identical), CBR1 (16% identical), CBR3 (16% identical), DHRS4L2 (16% identical), and 1 more.
Diseases named in the same sentence as DHRS7 in open-access papers:
DHRS7 is named in the same sentence as 10 diseases in open-access papers, as found by Europe PMC text mining. Sharing a sentence is not in itself a finding about the gene and the disease. The quoted sentences say what the papers report.
prostate carcinoma (5 papers, 2010 to 2023). A carcinoma that arises from epithelial cells of the prostate gland. "An exogenous expression of DHRS7 in the PC3 prostate cancer cell line with normally low DHRS7 levels correspondingly decreases nuclear size." (PMID 38201261, 2023). "Here, we found that reduction in DHRS7 from the LNCaP prostate cancer cell line with normally high levels of DHRS7 increases nuclear size, potentially explaining the nuclear size increase observed in higher-grade prostate tumors where it is lost." (PMID 38201261, 2023). "The short-chain dehydrogenase/reductase (SDR) family member DHRS7 was suggested as a biomarker for use in prostate cancer grading because it is largely lost in higher-grade tumors." (PMID 38201261, 2023). "This study suggests a tumor-suppressor role for DHRS7 by modulating EGFR expression in prostate cancer." (PMID 35804847, 2022). "Despite the fact that DHRS7 can inactivate 5α-dihydrotestosterone, its effect on prostate cancer cells seems to be unrelated to androgen metabolism." (PMID 35804847, 2022). "Several microarray studies of prostate cancer (PCa) samples have suggested altered expression of the “orphan” enzyme short-chain dehydrogenase/reductase DHRS7 (retSDR4, SDR34C1)." (PMID 26311046, 2015). "Several studies have found that DHRS7 activity is reduced in prostate cancer patients; nonetheless, the expression of DHRS7 has been linked to cell proliferation and adhesion, suggesting that this molecule may operate as a tumor suppressor." (PMID 36276963, 2022). "We studied the role of DHRS7, a potential tumor suppressor with currently unknown physiological function, in prostate cancer cells using proteome and gene expression analyses." (PMID 35804847, 2022). "Instead, KEGG pathway annotation and filtering for proteins associated with “prostate cancer” revealed several proteins, like EGFR, which may help to link DHRS7 to PCa." (PMID 35804847, 2022). "Importantly, DHRS7 expression negatively correlates with EGFR expression and positively with survival rates in prostate cancer patients." (PMID 35804847, 2022).
gastric cancer (2 papers, 2022). A primary or metastatic malignant neoplasm involving the stomach. "In the case of gastrointestinal malignancies, increased DHRS7 expression is linked to a poor prognosis in individuals with gastric cancer." (PMID 36276963, 2022).
fibrosarcoma (1 paper, 2023). A malignant mesenchymal fibroblastic neoplasm affecting the soft tissue and bone. "Because DHRS7 was previously confirmed in the inner nuclear membrane of HT1080 cells (derived from a fibrosarcoma), our result indicates that its catalytic domain could face the nucleoplasm and therefore directly contribute to nuclear functions." (PMID 38201261, 2023).
lung carcinoma (1 paper, 2022). "All four immune cells are favorably linked with DHRS7 in lung cancer." (PMID 36276963, 2022).
Renal clear cell carcinoma (1 paper, 2022). "Renal clear cell carcinoma (KIRC) is one malignancy whose development and prognosis have been associated with aberrant DHRS7 expression." (PMID 36276963, 2022).
cancer (7 papers, 2014 to 2025). A tumor composed of atypical neoplastic, often pleomorphic cells that invade other tissues. "Nevertheless, the mechanism underlying the effects of DHRS7 on cancer cell (and normal cell) behavior remains unknown and warrants further research." (PMID 26311046, 2015). "The inverse correlation between DHRS7 and EGFR expression and the increase in EGFR expression and phosphorylation following DHRS7 knockdown could be of therapeutic relevance as the loss of DHRS7 may alter the sensitivity of the cancer cells towards antibodies and inhibitors of EGFR." (PMID 35804847, 2022). "We predict that these nuclear size changes drive the reported increased cell migration of LNCaP cells knocked down for DHRS7 as we previously showed that correcting the nuclear size defect in several cancer cell lines reduced cell migration/invasion." (PMID 38201261, 2023). "The exogenously expressed protein was previously shown to target the inner nuclear membrane in the HT1080 fibroblast cancer cell line; however, functional DHRS7 has been assumed to localize in the endoplasmic reticulum (ER) in PCa models." (PMID 38201261, 2023). "In our research, we discovered that DHRS7 is abnormally expressed in pan-cancer patients and has an impact on their survival." (PMID 36276963, 2022). "As a result, uncovering the pan-cancer relationships between DHRS7 expression and the TME is crucial." (PMID 36276963, 2022). "Our results show that DHRS7 is abnormally expressed in pan-cancer patients, which influences their survival." (PMID 36276963, 2022). "Nevertheless, some of the closest relatives of DHRS7, namely 11β-HSD and 17β-HSD enzymes, have been associated with cancer." (PMID 26311046, 2015). "In conclusion, our in vitro experiments provide compelling evidence for DHRS7 as a key regulator of PCa cancer cell properties." (PMID 26311046, 2015). "In KIRC and pan-cancer studies, DHRS7 has emerged as an immune-related prognostic biomarker." (PMID 41522628, 2025). "In addition, DHRS7 expression was found to be positively correlated with MSI in seven cancer types, including UCEC, THYM, and LGG, and negatively correlated with MSI in SARC, LUAD, BRCA, and THCA." (PMID 36276963, 2022). "It remains to be investigated whether DHRS7 might play a role in the production of androgens via the backdoor pathway 32 or whether it indirectly stimulates androgen-dependent cancer cell proliferation." (PMID 26311046, 2015). "Although the underlying mechanism remains unknown, it has been recently suggested that DHRS7 may promote de novo androgen synthesis, thus directly influencing the activation of the AR, thereby stimulating cancer progression." (PMID 26311046, 2015). "Given that EP reverses the direction of cancer-associated nuclear size changes in PC3, and that DHRS7 expression status recapitulates nuclear size changes in progressing PCa, we sought to investigate whether EP acts in a DHRS7-dependent way to regulate nuclear size." (PMID 38201261, 2023). "In the present study, we decided to further analyze the effect of DHRS7 knockdown on EGFR because of its importance in cell signaling and cancer treatment." (PMID 35804847, 2022). "First, DHRS7 expression levels in LNCaP, PC3, and BPH1 cells were evaluated and then the effect of DHRS7 knockdown on key characteristics of aggressive cancer phenotypes like cell proliferation, migration and adhesion was investigated." (PMID 26311046, 2015). "Additionally, DHRS7 has emerged as an immune-related prognostic biomarker for both kidney renal clear cell carcinoma (KIRC) and pan-cancer." (PMID 41522628, 2025). "Microarray-based gene expression profiling studies suggested that DHRS7 expression is often decreased or even lost in PCa 9–11, raising the question about its potential role in tumor progression, however, its role in cancer has not been elucidated." (PMID 26311046, 2015).
cancer (continued). "However, the aberrant expression of DHRS7 in cancer and the relationship between DHRS7 and TME are not well understood, which calls for more research and could lead to novel clinical targets for tumor prognosis and treatment." (PMID 36276963, 2022). "However, the role of DHRS7 in PCa is largely unknown and the impact of DHRS7 modulation on cancer cell properties has not yet been studied." (PMID 26311046, 2015). "The results of the present study revealed a negative correlation between the expression of DHRS7 and the transmembrane tyrosine kinase EGFR, a receptor involved in various cancers, and which has increased expression in PCa disease progression." (PMID 35804847, 2022).
tumor (5 papers, 2015 to 2023). "Following that, we looked into the association between DHRS7 expression and tumor stage and discovered that ASF1B expression was substantially correlated with tumor stage in seven malignancies, including KIRC, KIRP, LUSC, READ, SKCM, STAD, and THCA." (PMID 36276963, 2022). "This shows that DHRS7 has a role in immune function and is associated with tumor occurrence and treatment." (PMID 36276963, 2022). "Based on these results, further research is needed to evaluate the potential role of DHRS7 as a tumor suppressor and whether its loss-of-function promotes PCa progression and metastasis." (PMID 26311046, 2015). "All of these suggest that DHRS7 expression is lowered, which reduces immune function, enhances immune escape, and promotes tumor progression." (PMID 36276963, 2022). "A tumor-suppressor role of DHRS7 was further supported by observations that DHRS7 expression is abolished in metastatic PCa compared to primary PCa, and its expression declines with PCa progression as measured by the Gleason pattern." (PMID 35804847, 2022). "When compared to normal tissue in KIRC, both unpaired and paired samples demonstrated lower expression of DHRS7 in tumor tissue." (PMID 36276963, 2022). "This study clearly points to the role of DHRS7 as a tumor-suppressor in PCa and should stimulate further work to more profoundly understand this fundamental link and elucidate the tumor-suppressor role of DHRS7 in PCa." (PMID 35804847, 2022). "Here, we investigated DHRS7 expression in normal human prostate and PCa tissue samples at different tumor grade using tissue microarray and immunovisualization." (PMID 26311046, 2015). "We found that DHRS7 protein expression decreases alongside tumor grade, as judged by the Gleason level, in PCa tissue samples." (PMID 26311046, 2015). "Together, these results suggested that DHRS7 may act as a tumor suppressor in early-stage PCa by lowering intratumoral 5α-DHT concentrations." (PMID 35804847, 2022). "The biological importance of DHRS7 expression in various tumor tissues was investigated using GESA." (PMID 36276963, 2022). "Therefore, we decided to study the expression of DHRS7 in normal human prostate and in PCa tissue samples at different tumor stages." (PMID 26311046, 2015). "According to our results and those of others, DHRS7 possesses tumor suppressor functions in PCa." (PMID 26311046, 2015). "A better understanding of the tumor-suppressive role of DHRS7 may lead to the identification of a novel therapeutic PCa target and/or the potential development of a diagnostic application." (PMID 26311046, 2015). "Hence, DHRS7 down-regulation may be sufficient to explain most of the nuclear size increase that occurs as the tumor grade increases in PCa." (PMID 38201261, 2023). "In our study, we examined the significant influence of DHRS7 on the tumor microenvironment (TME) and tumor progression using an overall predictable and prognostic evaluation approach." (PMID 36276963, 2022). "It was clear that as the tumor progressed, the expression of DHRS7 decreased, regardless of the M0&M1, N0&N1, T1&T3, T1&2, or pathological stage." (PMID 36276963, 2022). "The finding that DHRS7 is able to inactivate 5α-DHT, the most potent AR ligand in men, to 3α-Adiol led to the hypothesis that DHRS7 acts as a tumor-suppressor in PCa by lowering intratumoral 5α-DHT levels." (PMID 35804847, 2022). "Microarray expression data from three independent studies on human PCa tissues suggested that the levels of the short-chain dehydrogenase/reductase (SDR) enzyme DHRS7 (also known as retSDR4 and under the nomenclature name SDR34C1) 8 are frequently altered in this tumor 9–11." (PMID 26311046, 2015). "We could see that the expression level of DHRS7 was lower in stage III than in stages I and II (p = 0.014, p = 0.0012) and that the expression level of stage IV was lower than that of stage II (p = 0.027) as the tumor advanced and decreased." (PMID 36276963, 2022).
tumor (continued). "Using KIRC as an example, we discovered a negative correlation between DHRS7 expression and immunological assessments, suggesting that this substance might be used as a tumor biomarker." (PMID 36276963, 2022). "Overall, DHRS7 expression was higher in non-tumor samples compared to tumor samples and, accordingly, EGFR expression was higher in tumor samples compared to non-tumor prostate samples." (PMID 35804847, 2022). "Using KIRC as an example, we discovered a negative connection between DHRS7 expression and TMB, as well as immunological ratings, implying that this chemical could be used as a tumor biomarker." (PMID 36276963, 2022).
DHRS7 also shares sentences with these, for which no sentence is quoted: necrotizing enterocolitis (1 paper); Obesity (1); prostate tumors (1).